GNB1 (G protein subunit beta 1)
Diseases named in the same sentence as GNB1 in open-access papers (continued):
Sharing a sentence is not in itself a finding about the gene and the disease.
cancer (11 papers, 2016 to 2025). A tumor composed of atypical neoplastic, often pleomorphic cells that invade other tissues. "For example, many studies have demonstrated that GNB1 is involved in the progression and drug resistance of multiple cancer types." (PMID 39751645, 2024). "Meanwhile, it was also discovered that the restraining of SHK on cancer cells was achieved through miR-545-3p/GNB1 signaling axis, and in vivo experimental results further demonstrated SHK had clearly repressive effect on tumor formation." (PMID 35192430, 2022). "Further, the G family proteins, GNB1 and GNB2 are implicated in cancer proliferation, survival, invasion, metastasis, survival and resistance." (PMID 32350346, 2020). "Meanwhile, few reports on the action of GNB1 in cancer as well." (PMID 35192430, 2022). "GNB1 also exerts a crucial part in human cancer in the past few years." (PMID 35192430, 2022). "Taken together, our results suggested that GNB1 up-regulation may be considered as a novel potential diagnostic biomarker in CRC patients of different races, cancer stages, genders, age groups, and body weights." (PMID 34473751, 2021). "Of note, similar to GNB1 both CDC42 and CHD5 were found to be highly methylated (methylated read count >700) in the BOCA-FR cancer cohort." (PMID 41345172, 2025). "The results also revealed a decrease in KCNA2, SNCG, and TGFB2 levels with a simultaneous increase in GNB1, CXCL12, SNCA, and OPRK1 expression in G2 cancer compared to control." (PMID 34768458, 2021). "In the present study, we observed the significant (p<0.05) up-regulation of GNB1 mRNA in COAD patients of different clinicopathological features including different races, cancer stages, genders, age groups, and body weights as compared to the normal controls." (PMID 34473751, 2021). "Some proteins of the guanine nucleotide‐binding protein subunits GNAQ (Gqα), GNAS (Gs‐α), GNB1(Gβ1), and GNA13 (Gα) were overrepresented in the Circadian entrainment pathway as well as in cancer pathway." (PMID 31282103, 2019). "For example, the following top 100 MDS genes can be mentioned that are not yet covered by approved or experimental cancer or antineoplastic drugs [according to DrugBank, DGIdb, FDA6, HMDB, Tocris7, GeneCards databases]: GRB2, SOS1,SOS2, SHC1, GNB1, CREB1, GNG2, GNAQ, GNB5, GNAI2." (PMID 30728774, 2019).
tumor (10 papers, 2009 to 2025). "Within this research, GNB1 in CRC was augmented and was reversely linked with miR-545-3p;The elevation of GNB1 turned around the tumor suppressor effect of SHK on CRC cells, augmented the CRC cell advancement with declined G0/G1 phase cells, apoptosis and autophagy." (PMID 35192430, 2022). "A series of biological function studies revealed that AFAP1-AS1 and GNB1 play a carcinogenic role in RB, whereas miR-545-3p acts as a tumor suppressor." (PMID 35193469, 2022). "The enhanced expression of GNB1 in CESC tissues was also confirmed by immunohistochemical staining of GNB1 in CESC tissues or non-tumor tissues." (PMID 32766125, 2020). "MYH9, GNB1, and ALOX12B were negatively associated with the tumor response, which represented biomarkers of poor outcomes, while HSD17B4 was positively associated with the tumor response." (PMID 36612298, 2023). "Consequently, SHK was available to repress the tumor progression in part via modulating the miR-545-3p/GNB1 axis." (PMID 35192430, 2022).
neurodevelopmental disorder (7 papers, 2020 to 2025). A behavioral and cognitive disorder with onset during the developmental period that involves impaired or aberrant development of intellectual, motor, or social functions. "Deletion of GNB1 can lead to associated neurodevelopmental disorders." (PMID 40285432, 2025). "Therefore, additional examples of haploinsufficiency in humans associated with relevant phenotypes are needed as well as protein quantitation in patient samples to concretely associate haploinsufficiency in GNB1 with neurodevelopmental disorder." (PMID 32918542, 2020). "Missense variants in GNB1 are associated with a complex neurodevelopmental disorder." (PMID 32918542, 2020). "Polymorphisms or mutations in GNB1, GNB2, and GNB5 genes were reported to be associated with neurodevelopmental disorders." (PMID 36077181, 2022). "While GNB1 showed no significant changes, its potential role in neurodevelopmental disorders warrants additional investigation." (PMID 40873676, 2025).
neurological diseases (5 papers, 2021 to 2025). "GNB1 is frequently associated with human neurological diseases." (PMID 35192430, 2022). "Based on these findings and the results for GNB1 we conclude that CNVs through its effect on protein receptor complexes has an important role to play in neurological diseases and maintaining homeostasis in the brain." (PMID 41345172, 2025).
infection (3 papers, 2012 to 2025). The state of being infected such as from the introduction of a foreign agent such as serum, vaccine, antigenic substance or organism. "Therefore, it is unlikely that specific GNB1 genotypes predispose individuals to infection with HCV-1 and HCV-2 or contribute to spontaneous virus elimination." (PMID 23171003, 2012). "Furthermore, many chemokine receptors like CCR4, CCL14, XCR1 along with the adaptor molecules CRKII and ELMO1 were downregulated during initial and mid stages of infection, and in contrast, some G protein signaling molecules such as GNAI, GNB1, FAK and FAK2 were upregulated in infected fish." (PMID 33177569, 2020).
movement disorder (3 papers, 2022 to 2025). Neurological conditions resulting in abnormal voluntary or involuntary movement, which may impact the speed, fluency, quality and ease of movement. "The dystonic epochs and coordination deficits observed in KCTD5 KO reflect hyperkinetic movement disorder pathology observed in patients with polymorphisms in signal transduction machinery, including DRD2, GNAL, GNAO1, and GNB1." (PMID 40233107, 2025). "Only three reports about pharmacological treatment in patients with GNB1 variants are available, and no drugs have been reported to dramatically improve movement disorder." (PMID 36003298, 2022).
genetic disease (2 papers, 2022 to 2024). "GNB1 encephalopathy (GNB1-E) is a rare genetic disease caused by pathogenic variants in the G Protein Subunit Beta 1 (GNB1) gene." (PMID 38674235, 2024). "We collected and reviewed 74 articles (17 for GNB1, 46 for GNAO1, 6 for PDE10A, 2 for PDE2A, and 3 for HCPCA) describing motor, epileptic, and developmental phenotype of patients with genetic disorders of GPCRs–cAMP signaling pathway." (PMID 36003298, 2022).
adenocarcinoma (1 paper, 2023). A common cancer characterized by the presence of malignant glandular cells. "In 230 patients with adenocarcinoma from the TCGA cohort, higher expressions of MYH9, GNB1, and ALOX12B were associated with poor overall survival outcomes, while higher expression of HSD17B4 was associated with better survival outcomes." (PMID 36612298, 2023).
hematological neoplasm (1 paper, 2022). "GNB1 mutations have been found in different hematological neoplasm cell lines and are thought to increase the activation of AKT/ERK/mTOR signaling." (PMID 36003298, 2022).
GNB1 also shares sentences with these, for which no sentence is quoted: Ataxia (3 papers); acute myeloid leukemia (2); Behavioral Disorders (2); Chorea (2); myeloid malignancies (2); Myoclonus (2); anorexia nervosa (1); asthma (1); bipolar disorder (1); bladder cancer (1); cardiovascular disease (1); chronic hepatitis C (1); colorectal tumors (1); convulsion (1); craniosynostosis (1); cutaneous mastocytosis (1); Dyskinesia (1); Ewing sarcoma (1); gastric cancer (1); hereditary spastic paraplegia (1); Hyperkeratosis (1); Hypertension (1); Hypsarrhythmia (1); kidney cancer (1); kidney disease (1); liver disease (1); liver fibrosis (1); lung diseases (1); metabolic disease (1); migraine with aura (1).
A further 19 diseases each share a sentence with GNB1 in 1 paper.